KCNG1 (potassium voltage-gated channel modifier subfamily G member 1)
Description:
Potassium channel subunit that does not form functional channels by itself.
Synonyms: Kv6.1; kH2; K13; KCNG
Tractability: Small molecule: an approved drug acts on it; it belongs to a druggable protein family. Antibody: its Gene Ontology location is reachable by antibodies, with high confidence; UniProt places it where antibodies can reach, with medium confidence; UniProt predicts a signal peptide or a membrane-spanning region. PROTAC: ubiquitination databases record sites on it.
Gene: Protein-coding gene on chromosome 20 (51,003,655 to 51,023,244, reverse strand). Ensembl gene ENSG00000026559.
Subcellular location: Cell membrane
Subcellular location (Human Protein Atlas): Vesicles
Pathways (Reactome):
Neuronal System: Voltage gated Potassium channels
Gene Ontology:
Molecular function: potassium channel regulator activity; monoatomic ion channel activity; voltage-gated potassium channel activity
Biological process: action potential; potassium ion transmembrane transport; potassium ion transport; regulation of potassium ion transmembrane transport; monoatomic ion transport; protein homooligomerization; regulation of potassium ion transport; transmembrane transport
Cellular component: voltage-gated potassium channel complex; membrane; plasma membrane
Genetic constraint (gnomAD): Loss-of-function variants: 15 observed, 24.73 expected, observed/expected ratio (o/e) 0.61, 90% interval 0.41 to 0.93. The upper end of that interval is the gene's LOEUF score, 0.93, which puts it in group 3 of 6, group 1 being the genes least tolerant of losing a copy. Missense variants: 399 observed, 615.46 expected, observed/expected ratio (o/e) 0.65, 90% interval 0.6 to 0.7. Synonymous variants: 335 observed, 298.44 expected, observed/expected ratio (o/e) 1.12, 90% interval 1.03 to 1.23.
Homologues: Orthologues: chimpanzee KCNG1 (100% identical), macaque KCNG1 (99% identical), pig KCNG1 (95% identical), guinea pig KCNG1 (95% identical), dog KCNG1 (94% identical), mouse Kcng1 (93% identical), rat Kcng1 (93% identical), tropical clawed frog kcng1 (76% identical), zebrafish kcng1 (70% identical). Paralogues in human: KCNG4 (56% identical), KCNG2 (51% identical), KCNB2 (37% identical), KCNG3 (35% identical), KCNS3 (32% identical), KCNS2 (31% identical), KCNS1 (31% identical), KCNV1 (30% identical), KCND1 (30% identical), KCNV2 (29% identical), KCNC3 (29% identical), and 19 more.
Diseases named in the same sentence as KCNG1 in open-access papers:
KCNG1 is named in the same sentence as 12 diseases in open-access papers, as found by Europe PMC text mining. Sharing a sentence is not in itself a finding about the gene and the disease. The quoted sentences say what the papers report.
diabetes (1 paper, 2007). "The diabetes-associated potassium ion channel Kcng1 was also discovered by RIT, strengthening this hypothesis." (PMID 17490475, 2007).
head and neck squamous cell carcinoma (1 paper, 2023). A squamous cell carcinoma that arises from any of the following anatomic sites: lip and oral cavity, nasal cavity, paranasal sinuses, pharynx, larynx, and salivary glands. "In contrast, KCNG1, a gene involved in fatty acid metabolism (FAM), has a strong correlation with the prognosis of head and neck squamous cell carcinoma." (PMID 38327905, 2023).
Myelodysplasia (1 paper, 2021). Clonal hematopoietic stem cell disorders characterized by dysplasia (ineffective production) in one or more hematopoietic cell lineages, leading to anemia and cytopenia. "Physiological functions of KCNG1 are largely unknown, by similarity, therefore, it is plausible that the identified mutation in our study is also the underlying cause for the craniofacial dysmorphism and myelodysplasia associated with hydrosyringomyelia." (PMID 34828398, 2021).
cancer (2 papers, 2009 to 2024). A tumor composed of atypical neoplastic, often pleomorphic cells that invade other tissues. "Of these PARD6B, BCAS4, and KCNG1 are expressed greater than two-fold higher in cancer samples with the amplification relative to normal." (PMID 19419571, 2009). "Additionally, KCNG1 was identified as a driver gene in cancer by NBDep but has not been previously reported in both non-missense and amplification driver genes." (PMID 38195844, 2024).
genetic diseases (1 paper, 2025). "Limb-related genetic diseases are often variably penetrant and thus a clear role of KCNG1 might be difficult to sort out as other modifiers may be present." (PMID 41241096, 2025).
infection (1 paper, 2025). The state of being infected such as from the introduction of a foreign agent such as serum, vaccine, antigenic substance or organism. "Notably, genes such as Cyp26b1, Dbp, Kcng1, Cdca7l, Paxip1, Stxbp2 and Gpi1 were also observed to be significantly up-regulated (p<0.05) in the hMHC mice on various days post-infection." (PMID 40822594, 2025).
KCNG1 also shares sentences with these, for which no sentence is quoted: fragile X syndrome (1 paper); Intellectual disability (1); Neurodevelopmental delay (1); neurologic disorder (1); pneumonia (1); syringomyelia (1).